MED15 (mediator complex subunit 15)
Description:
Component of the Mediator complex, a coactivator involved in the regulated transcription of nearly all RNA polymerase II-dependent genes. Mediator functions as a bridge to convey information from gene-specific regulatory proteins to the basal RNA polymerase II transcription machinery. Mediator is recruited to promoters by direct interactions with regulatory proteins and serves as a scaffold for the assembly of a functional preinitiation complex with RNA polymerase II and the general transcription factors. Required for cholesterol-dependent gene regulation. Positively regulates the Nodal signaling pathway.
Synonyms: ARC105; TIG-1; CTG7A; PCQAP; TIG1; TNRC7; CAG7A
Tractability: Small molecule: a structure with a bound ligand is known. PROTAC: UniProt records ubiquitination sites on it; ubiquitination databases record sites on it; its protein half-life has been measured.
Gene: Protein-coding gene on chromosome 22 (20,495,913 to 20,587,632, forward strand). Ensembl gene ENSG00000099917.
Subcellular location: Cytoplasm; Nucleus
Subcellular location (Human Protein Atlas): Nucleoplasm
Pathways (Reactome):
Developmental Biology: Transcriptional regulation of white adipocyte differentiation
Disease: RSV-host interactions
Gene expression (Transcription): Generic Transcription Pathway
Metabolism: PPARA activates gene expression
Gene Ontology:
Molecular function: protein binding; transcription coregulator activity
Biological process: positive regulation of transcription elongation by RNA polymerase II; positive regulation of transcription initiation by RNA polymerase II; RNA polymerase II preinitiation complex assembly; regulation of DNA-templated transcription
Cellular component: core mediator complex; membrane; nucleoplasm; nucleus; cytoplasm
Genetic constraint (gnomAD): Loss-of-function variants: 41 observed, 119.51 expected, observed/expected ratio (o/e) 0.34, 90% interval 0.27 to 0.44. The upper end of that interval is the gene's LOEUF score, 0.44, which puts it in group 1 of 6, group 1 being the genes least tolerant of losing a copy. Missense variants: 740 observed, 1,041.2 expected, observed/expected ratio (o/e) 0.71, 90% interval 0.67 to 0.75. Synonymous variants: 435 observed, 420.44 expected, observed/expected ratio (o/e) 1.03, 90% interval 0.96 to 1.12.
Homologues: Orthologues: chimpanzee MED15 (99% identical), macaque MED15 (99% identical), rat Med15 (92% identical), mouse Med15 (91% identical), rabbit MED15 (91% identical), dog MED15 (90% identical), pig MED15 (89% identical), guinea pig MED15 (80% identical), tropical clawed frog med15 (71% identical), zebrafish med15 (61% identical), Drosophila melanogaster MED15 (30% identical).
Diseases named in the same sentence as MED15 in open-access papers:
MED15 is named in the same sentence as 53 diseases in open-access papers, as found by Europe PMC text mining. Sharing a sentence is not in itself a finding about the gene and the disease. The quoted sentences say what the papers report.
renal cell carcinoma (5 papers, 2021 to 2025). "Med15 is associated with worse survival rates in renal cell carcinoma (RCC), and its upregulation significantly increases tumour proliferation, migration and invasion." (PMID 38493218, 2024). "MED15 is part of the multiprotein mediator complex, which plays a cancer-promoting role in urothelial bladder cancer (BCa) and renal cell carcinoma (RCa)." (PMID 34642262, 2021). "In the specific context of renal cell carcinoma, MED15 has been identified as a fusion partner of TFE3 in a rare subtype, suggesting that aberrant activation of the TFE3-MED15 fusion protein may contribute to tumorigenesis." (PMID 39947475, 2025). "Concerning renal cell carcinoma, preclinical models have shown that HIF2α-dependent MED15 over-expression may promote lipid deposition and tumor progression through sterol regulatory element binding protein (SREBP) coactivation via the AKT pathway." (PMID 39410016, 2024). "To investigate this further, we generated MED15 KO colon cancer HCT116 cells and renal cell carcinoma pVHL-mutant 786-O cells using CRISPR/Cas9 technology." (PMID 39947475, 2025). "Although over the past 30 years, numerous fusion partners have been identified in TFE3-rearranged renal cell carcinoma and PEComa, ASPL/ASPSCR1, PRCC, SFPQ, NONO, and MED15 remain the most frequent in both groups of neoplasms." (PMID 39410016, 2024).
prostate carcinoma (4 papers, 2015 to 2025). A carcinoma that arises from epithelial cells of the prostate gland. "MED15 acts as an oncogene in numerous types of cancer, including hepatocellular carcinoma, prostate cancer, head and neck squamous cell carcinoma, bladder carcinoma, and renal carcinoma, to promote tumor progression." (PMID 38649345, 2024). "For example, in castration-resistant prostate cancer, MED15 is frequently overexpressed and correlates with pSmad3 expression, a downstream target indicating activation of the TGF-β signaling cascade." (PMID 26377566, 2015).
schizophrenia (4 papers, 2008 to 2024). A major psychotic disorder characterized by abnormalities in the perception or expression of reality. "The human orthologue of Med15 is coupled with pathological conditions, such as cancer lipid metabolism disorders, autism, schizophrenia or DiGeorge syndrome, which is one of the most frequent genetic deletions coupled with intellectual disability." (PMID 39353569, 2024).
head and neck squamous cell carcinoma (3 papers, 2019 to 2024). A squamous cell carcinoma that arises from any of the following anatomic sites: lip and oral cavity, nasal cavity, paranasal sinuses, pharynx, larynx, and salivary glands. "According to the previous studies, MED15 was overexpressed in 35% of primary head and neck squamous cell carcinoma and was known to be involved in castration-resistant prostate cancer." (PMID 31828108, 2019).
oral squamous cell carcinoma (3 papers, 2020 to 2022). "MED15-PrLD forms intracellular inclusions in different human cell lines, including laryngeal and oral squamous cell carcinoma, two tumors with MED15 implication." (PMID 33772081, 2021). "Factors associated with the expression of oral squamous cell carcinoma (OSCC) biomarkers “CD16, CD57, TGF-β1, and MED15” are not assessed, except in few controversial studies of some of these biomarkers." (PMID 36340330, 2022).
oropharyngeal cancer (3 papers, 2021 to 2025). Carcinoma, predominantly squamous cell, arising from the epithelial cells of the oropharynx. "Conversely, the decreased expression of MED15 protein is implicated in uterine leiomyosarcomas regardless of mutational status and MED15 is considered a tumor suppressor in oral/oropharyngeal cancers." (PMID 35096564, 2021).
clear cell renal cell carcinoma (2 papers, 2024 to 2025). "Indeed, MED15 deletion significantly suppressed tumor growth in vitro and xenograft models of colorectal and renal clear cell carcinoma." (PMID 39947475, 2025). "Interestingly, we observed that MED15 deficiency upregulated CPT1A, a key HIF target gene and fatty acid oxidation enzyme known to be suppressed by HIF in renal clear cell carcinoma." (PMID 39947475, 2025).
DiGeorge syndrome (2 papers, 2020 to 2024). "22q11 proximal deletion, also known as DiGeorge syndrome or velocardiofacial syndrome, involves more than 30 Mendelian genes; potential genes such as TBX1, COMT, UFD1L, GNB1L, TRXR2, MED15, and RANBP1 were researched to explore the phenotype/CNV correlation." (PMID 32863884, 2020).
Obesity (2 papers, 2024 to 2025). Accumulation of substantial excess body fat. "MED15, a subunit of the mediator complex, has been identified to be associated with multidrug resistance, obesity, and tumor aggressiveness." (PMID 38649345, 2024). "Overexpression of MED15 has been shown to exacerbate obesity and lipid metabolism disorders induced by high-fat diets through promotion of cholesterol and fatty acid synthesis pathways." (PMID 40940746, 2025). "Inhibition of the interaction between MED15 and SREBPs might be a novel therapeutic strategy for the treatment of various diseases with aberrant lipid metabolism, such as obesity and cancers." (PMID 38649345, 2024). "Preclinical studies have demonstrated that small-molecule inhibitors BF175 targeting MED15–KIX interaction significantly improved body weight and lipid profiles in murine obesity models." (PMID 40940746, 2025).
oral cancer (2 papers, 2020 to 2022). "RASSF1A, TIMP3, and PCQAP/MED15 were presented as a four-panel approach for the earliest possible identification of the incidence of oral cancer (OC)/OPC." (PMID 33521000, 2020).
renal carcinoma (2 papers, 2024 to 2025). A carcinoma arising from the epithelium of the renal parenchyma or the renal pelvis. "While some studies suggest an oncogenic role for MED15, potentially linking it to the development of breast, prostate, and renal cancers, the underlying mechanisms are poorly understood." (PMID 39947475, 2025). "Functionally, MED15 deficiency attenuated the proliferation of colon and renal cancer cells in vitro and tumor growth in vivo." (PMID 39947475, 2025). "Our work demonstrates that MED15 promotes lipid deposition and tumor progression in renal carcinoma by altering lipid synthesis pathways." (PMID 38649345, 2024). "In addition, sequencing of stable HIF-2α knockdown renal cancer cells identified MED15, which was proven to promote lipid accumulation in ccRCC." (PMID 38649345, 2024).
testicular germ cell tumor (2 papers, 2015 to 2016). A germ cell tumor arising from the testis. "Furthermore, a recently published study of our working group, which was deduced on the Oncomine transcriptome, was able to confirm the frequently occurring MED15 overexpression in testicular germ cell tumors on protein level." (PMID 27050271, 2016). "In contrast, non-seminomatous germ cell tumors (NSGCT) exhibited a significantly higher MED15 expression and positivity index as compared to tumor-free testes and SEM." (PMID 26377566, 2015).
Alzheimer disease (1 paper, 2025). A progressive, neurodegenerative disease characterized by loss of function and death of nerve cells in several areas of the brain leading to loss of cognitive function such as memory and language. "Consistently, several age-related diseases, such as lung cancer, atherosclerosis, and Alzheimer’s disease, were predicted to be associated with upregulated genes in MED15 T603D mutant cells." (PMID 40825935, 2025).
campomelic dysplasia (1 paper, 2024). "Potentially pathogenic variants were discovered in the FAS and pFAS groups, including those known to cause craniofacial malformations, such as SOX9 (Campomelic Dysplasia), STRA6 (Matthew–Wood), CHD7 (CHARGE), MID1 and MED15 (Opitz–Kaveggia syndrome), and several 22q11.2DS genes." (PMID 38785976, 2024).
cognitive decline (1 paper, 2025). "Overall, our study indicates that MED15 T603 phosphorylation serves as a control switch for SASP production, which underlies tissue aging and cognitive decline and provides a novel target for age-related pathogenesis." (PMID 40825935, 2025).
colorectal cancer (1 paper, 2025). A primary or metastatic malignant neoplasm that affects the colon or rectum. "Analysis of The Cancer Genome Atlas (TCGA) datasets revealed a positive correlation between MED15 expression and the expression of HIF target genes, including ENO1, HK2, and VEGFA, in renal and colorectal cancers." (PMID 39947475, 2025).
endometrial cancer (1 paper, 2019). Primary or metastatic malignant neoplasm involving the endometrium (mucous membrane that lines the endometrial cavity). "Although PCQAP/MED15 methylation in HNSCC was identified and validated recently, it is frequently implicated in prostate and endometrial cancer etiologies." (PMID 31013839, 2019).
insulinoma (1 paper, 2019). "Similarly, mouse Med15 showed zinc induced binding to the regulatory regions of two genes in MIN6 insulinoma cells; although we did not succeed in effectively depleting Med15 in these cells with transfected siRNAs, we found that these genes are induced by zinc." (PMID 31815936, 2019).
lung adenocarcinoma (1 paper, 2019). A carcinoma that arises from the lung and is characterized by the presence of malignant glandular epithelial cells. "Studying a lung adenocarcinoma cell line that responds to cadmium, we found that MED15 depletion compromises the induction of a metallothionein and that MED15 directly binds the genomic regulatory region of this gene in cadmium enhanced fashion." (PMID 31815936, 2019). "Lastly, mammalian MDT-15 orthologs bind genomic regulatory regions of metallothionein and zinc transporter genes in a cadmium and zinc-stimulated fashion, and human MED15 is required to induce a metallothionein gene in lung adenocarcinoma cells exposed to cadmium." (PMID 31815936, 2019). "Moreover, mammalian MED15 is recruited to regulatory elements of cadmium and zinc-responsive genes in metal-stimulated fashion, and MED15 depletion blocks the induction of a cadmium responsive gene in lung adenocarcinoma cells." (PMID 31815936, 2019). "Collectively, these experiments suggest that mammalian MED15 proteins directly bind the promoters of cadmium and zinc responsive genes and are required for the induction of at least one cadmium responsive gene in lung adenocarcinoma cells." (PMID 31815936, 2019).
melanoma (1 paper, 2019). A malignant, usually aggressive tumor composed of atypical, neoplastic melanocytes. "To evaluate potential activators of DNFA expression, we depleted SREBF1, SREBF2, and co-activators MED15 and CREBBP28 with siRNAs, and examined DNFA expression across three melanoma cell lines: HT-144, A375 and MEL-JUSO." (PMID 31316083, 2019).
oral cavity cancer (1 paper, 2025). A primary or metastatic malignant neoplasm involving the oral cavity. "The study examined the methylation levels of the promoters of p16INK4a, RASSF1A, TIMP3, and PCQAP/MED15 in salivary DNA from patients with oral cavity cancer (OSCC) and pharyngeal cancer (OPC) with respect to their roles as risk factors for tumorigenesis." (PMID 40723410, 2025).
psoriasis (1 paper, 2024). An autoimmune condition characterized by red, well-delineated plaques with silvery scales that are usually on the extensor surfaces and scalp. "For psoriasis, an intronic variant (rs7291930) of the MED15 gene was selected under the inferred dominant mode." (PMID 38811555, 2024).
psoriatic arthritis (1 paper, 2024). Joint inflammation associated with psoriasis. "The MED15 gene was overexpressed in psoriatic arthritis patients." (PMID 38811555, 2024).
seminoma (1 paper, 2015). A radiosensitive malignant germ cell tumor found in the testis (especially undescended), and extragonadal sites (anterior mediastinum and pineal gland). "Furthermore, MED15 may play a role in the differentiation process between seminomas and non-seminomas." (PMID 26377566, 2015).
testicular cancer (1 paper, 2016). A primary or metastatic malignant neoplasm that affects the testis. "In testicular cancer only a single overexpression (MED15) was found; while other subunits were underexpressed (MED17, MED7, MED10, MED1)." (PMID 27050271, 2016).
tumor (13 papers, 2015 to 2025). "We further demonstrated that CPT1A inhibition rescued the reduction in tumor cell lipid content caused by MED15 loss, suggesting a novel role for MED15 in regulating hypoxia-induced lipid metabolism through the HIF-CPT1A axis." (PMID 39947475, 2025). "In addition, we found higher expression of MED15 in tumors, and this higher expression was associated with higher tumor stage." (PMID 38649345, 2024). "MED15 is expressed significantly higher in precursor lesion IGCNU as compared to tumor-free testes and may thus prove useful as a diagnostic feature to distinguish between benign and pre-malignant tissue." (PMID 26377566, 2015). "We observed a reduction in tumor cell LD upon MED15 deletion under both normoxic and hypoxic conditions." (PMID 39947475, 2025). "Mice harboring MED15-KO tumors exhibited significantly suppressed tumor growth compared to the WT controls." (PMID 39947475, 2025). "Depletion of HIF-2α or MED15 in ccRCC inhibited the formation of lipid droplets and tumor progression." (PMID 38649345, 2024). "HIF-2α promotes MED15 transcriptional activation by binding directly to the MED15 promoter region, further promoting lipid accumulation and tumor growth." (PMID 38649345, 2024). "We also found higher expression of MED15 in ccRCC than in normal kidney tissues in clinical samples, and the expression level of MED15 was positively correlated with tumor stage, suggesting that MED15 has the potential to be a biomarker of prognosis in ccRCC." (PMID 38649345, 2024). "In the present study, we found that MED15 induced lipid accumulation, cell proliferation, and tumor metastasis via transcriptional activation of SREBPs in ccRCC cells." (PMID 38649345, 2024). "Accordingly, overexpression of MED15 in HIF-2α knockdown cells restored lipid deposition and malignant tumor behavior phenotypes, suggesting that MED15-mediated lipid deposition and tumor progression in ccRCC are regulated by HIF-2α." (PMID 38649345, 2024). "The enriched biological process terms from the GO enrichment analysis showed that MED15 was related to not only the malignant behavior of tumor cells but also many lipid metabolism processes." (PMID 38649345, 2024). "HIF-2α promoted MED15 transcriptional activation by directly binding the MED15 promoter region, and MED15 overexpression significantly alleviated the lipid deposition inhibition and malignant tumor behavior phenotypes induced by HIF-2α knockdown." (PMID 38649345, 2024). "The results showed that both tumor weight and tumor volumes were significantly reduced in the MED15 knockdown group." (PMID 38649345, 2024). "Our study identified MED15 as a coactivator of SREBPs that promotes lipid accumulation and tumor progression in ccRCC and directly interacts with SREBPs through its KIX domain." (PMID 38649345, 2024). "Subsequently, RNA sequencing confirmed a fusion of MED15 gene exon 11 on chromosome 22 with TFE3 gene exon 6 in the tumor." (PMID 31828108, 2019). "We therefore evaluated the MED15 expression in tumor-free testis and TGCT subentities by immunohistochemical staining (IHC) on a large tissue microarray (TMA) cohort in order to evaluate a possible diagnostic and therapeutic value for MED15 in TGCT." (PMID 26377566, 2015). "In conclusion, the NSGCT significantly overexpress MED15 as compared to tumor-free testes and SEM (p < 0.001)." (PMID 26377566, 2015). "Given the established role of HIF in tumorigenesis, we hypothesized that MED15 might promote tumor growth through its regulation of HIF activity." (PMID 39947475, 2025). "MED15 promotes lipid-droplet production and tumor growth via direct SREBP interactions." (PMID 41451091, 2025). "MED15 promoted lipid deposition and tumor progression in ccRCC." (PMID 38649345, 2024). "The results showed that MED15 knockdown significantly reduced the lung metastasis of tumor cells." (PMID 38649345, 2024).